RAC1 (Rac family small GTPase 1)
Diseases named in the same sentence as RAC1 in open-access papers (continued):
Sharing a sentence is not in itself a finding about the gene and the disease.
breast carcinoma (continued). "In breast cancer cells, the proliferation and migration were significantly decreased when VASP was silenced by shRNA, which proves that VASP plays a role in cancer cell migration, and it may be associated with RAC1." (PMID 33171868, 2020). "Hence, we report a potential clinical relevance of ZNF750/RAC1 axis in breast cancer." (PMID 33298895, 2020). "Thus, it is worth exploring whether and how the Rac1/HIF-1α pathway is involved in SOX2-mediated breast cancer cell motility." (PMID 31462898, 2019). "Moreover, DOCK4 functions as a guanine nucleotide exchange factor for the GTPase Rac1, a key regulator of motility 14, 19, 20 and localises at actin‐rich protrusions in migrating breast cancer cells 19, while SNPs within the promoter region of DOCK4 have been detected in breast cancer." (PMID 30426503, 2019). "Therefore, it may be reasonable to speculate that the effect of NEDD9 on breast cancer cell migration is mediated by Rac1." (PMID 31462898, 2019). "Consequently, we analysed whether the reduction in RAC1 activity and in the invasive capacity of breast cancer cells induced by GA was dependent on the reduction in RAC1 SUMOylation." (PMID 31578236, 2019). "Consequently, IBP may regulate EMT and the movement of breast cancer cells via Rac1, RhoA and Cdc42 signaling pathways." (PMID 30754684, 2019). "Here, we examined whether Rac1 is also involved in hypoxia-induced breast cancer cell migration." (PMID 31462898, 2019). "Furthermore, Rac1 has been reported as an unfavorable prognostic factor in breast carcinomas." (PMID 29534468, 2018). "Expression of Rac1 may be partly regulated by locally produced estrogens in breast carcinomas." (PMID 29534468, 2018). "Therefore, it is suggested that ARHGAP15 may be expressed and have pivotal roles in the progress of human malignancies including breast carcinomas, affecting the Rac1 pathway." (PMID 29534468, 2018). "Moreover, novel drugs targeting the RAC1-GEF interaction are currently being developed using a rational design approach followed by evaluation for their anti-cancer properties in highly aggressive breast cancer cell lines." (PMID 28499439, 2017). "The alterations (gain/amplification) of RAC1 gene in ER-ve BC in the cBioPortal and poor outcome (RFS) data for ER-ve breast cancer cohort suggests the clinical significance of our finding in two independent data sets." (PMID 27902969, 2017). "Overall, these data suggest that RAC1 may represent a therapeutic target with broad potential in breast cancer, because it does not show a strong association with particular patient groups." (PMID 22689141, 2012). "Indeed, blockage of RAC1 induces cell cycle arrest or apoptosis in breast cancer cells." (PMID 21375780, 2011). "Rac1 constitutes the part which has a similar structure to nicotinamide adenine dinucleotide phosphate oxidase and, in this manner, participates in the control of the intracellular ROS machinery and modulates the migratory potential of breast cancer cells such as MCF-7." (PMID 23554696, 2011). "Therefore, it may be reasonable that LPA stimulates ROS generation in breast cancer cells through the activation of Rac1." (PMID 21209852, 2010). "Since WASP-family proteins, Arp-2/3 as well as their upstream regulators (Rac1, Cdc42) are known to be overexpressed in several invasive cancers including breast cancer, protrusion of tumour cells may be much less sensitive to loss of Pfn1 expression compared to vascular endothelial cells." (PMID 17940506, 2007). "Previous reports demonstrated that NSL-YHJ-2-27 depletes the cellular levels of some G-proteins, such as RAC1 and CDC42, in both lung and breast cancer cell lines." (PMID 40736275, 2025). "PLC-γ1 regulates Rac1 and CDC42 GTPases through I P3-induced calcium release, playing a critical role in breast cancer lung metastasis; inhibiting PLC-γ1 significantly reduces its metastatic potential." (PMID 40519297, 2025).
breast carcinoma (continued). "Statins suppress the HER2-induced AKT and extracellular signal-regulated kinase pathway by altering the localization of RAC1, thereby improving prognosis in patients with HER2-positive breast cancer." (PMID 40722632, 2025). "Vm depolarization promotes the redistribution of anionic phospholipid PIP2 and phosphatidylserine in the plasma membrane; this leads to the activation of Rac1 and further promotes EMT and regulates cell morphology and migration in breast cancer cells." (PMID 39673684, 2025). "The PRL-mediated activation of Nek3 contributes differentially to VAV2 signaling pathways involving Rac1 and signal transducer and activator of transcription 5 and implicates Nek3 during PRL-mediated actions in breast cancer." (PMID 40160874, 2025). "For instance, in breast cancer, Rac1 activation of aldolase A and ERK signaling triggers the non-oxidative PPP, enhancing nucleotide metabolism and shielding breast cancer cells from chemotherapy-induced DNA damage, thereby inducing chemotherapy resistance." (PMID 39624082, 2024). "There are also reports for the role of RAC1 and RAC1B in chemotherapy and targeted therapy resistance in cancers such as melanoma, lung cancer, breast cancer, and thyroid cancer, and this has been reviewed elsewhere." (PMID 39001533, 2024). "In breast cancer, AKR1B10 also promotes cell invasion and metastasis through stimulation of the FAK/Src/Rac1 signaling pathway." (PMID 38370384, 2024). "Altogether, our data suggest that the brain endothelium and EGF contribute to extravasation by promoting DOCK4/RAC1- and DOCK9/CDC42-mediated elongation and intercalation of breast cancer cells." (PMID 38762624, 2024). "Our proteomic analysis revealed proteomic profile alteration in MDA-MB-231 upon CB exposure that potentially led to breast cancer suppression, such as ZPR1/SHC1/MAPK-mediated cell proliferation and AXL/VAV2/RAC1-mediated cell motility pathways." (PMID 39527598, 2024). "Building upon these findings, our research has demonstrated that TNFAIP2 can induce the transcription of HIF1α via the Rac1-ERK-AP1 signaling pathway, thereby promoting tumor angiogenesis in breast cancer." (PMID 39532855, 2024). "This approach will help elucidate the potential reciprocal regulation of RAC1, CDC42 and their activating GEFs in brain homing breast cancer cells." (PMID 38762624, 2024). "In breast cancer, a positive feedback loop, based on mTORC2 targets Akt and PKC, potentiates Rac1 signals." (PMID 38270460, 2024). "Activation of Rac1 promotes cancer cell proliferation and migration via EMT in several types of cancers, such as melanoma, colorectal, lung, and breast cancers." (PMID 38424547, 2024). "This activation is dependent on soluble factors secreted by brain endothelial cells, and occurs via the RAC1 GEF DOCK4, which is required for breast cancer cell extravasation to the brain in vivo." (PMID 38762624, 2024). "We also show that brain endothelial cells promote paracrine stimulation of mesenchymal-like morphology of breast cancer cells via DOCK4, DOCK9, RAC1 and CDC42." (PMID 38762624, 2024). "RAC1 inhibition by NSC23766 induced G1 cell cycle arrest and apoptosis in breast cancer cells and inhibited the growth of prostate PC-3 cancer cells." (PMID 40396280, 2024). "Another PROTAC tractable target is Rac Family Small GTPase 1 (RAC1), inducing chemoresistance of breast cancer, interacts with co-opted E3 ligases MDM2 and XIAP, and potentially novel E3 ligases, ITCH and SMURF2." (PMID 37845222, 2023). "We found that upregulated Rho GTPases RAC1, CDC42, and RHOA participated in the TGF-beta signaling pathway in the breast cancer MCF-7 cell line treated with DOX." (PMID 37511111, 2023).
breast carcinoma (continued). "We previously found that TNFAIP2 was regulated by KLF5 and interacted with the small GTPases RAC1 and CDC42, thereby regulating the actin cytoskeleton and cell morphology in breast cancer cells." (PMID 37787041, 2023). "A dose-responsive drop in Rac1/Cdc42, WAVE2, phospho-Rac1/Cdc42, Arp2, and Arp3 was seen in MDA-MB-231 mammary tumor cells after 4 days of mangiferin therapy, in contrast to cells in respective control groups, according to a Western blot analysis." (PMID 38137424, 2023). "In breast cancer, TRAF4 promotes cancer cell migration and invasion through the Rac1 signaling pathway." (PMID 35242717, 2022). "While this has not been observed for FTL yet, it has been reported, that co-targeting of BRD4 and RAC1 disrupts the MYC/G9a axis and enhances the expression of FTH1 in breast cancer cells." (PMID 36231049, 2022). "Positive responding breast cancer cells upregulated ARHGAP22 by log2 fold change of 1.9, suggestive of Rac1 negative regulation." (PMID 35520391, 2022). "Incoherence to breast cancer restricts the cell proliferation, migration, and invasion of gastric cancer and induces apoptosis by targeting ITGB3, Rac1, and Sp1 mRNAs." (PMID 35511336, 2022). "Work in breast cancer cells extended this work by showing that GBP-2 inhibits cell migration and invadosome formation, accompanied by inhibition of Rac1 and activation of Cdc42 and RhoA." (PMID 35681772, 2022). "We also analyzed the expression levels of both RAC1 and BRD4 in different histological subtypes of breast cancer and nodal status." (PMID 34803511, 2021). "Meanwhile, EGFR (p = 0.008), RAC1 (p = 0.03) and VEGF-B (p = 0.0004) genes expression in mammary carcinoma tissue were higher in the high proliferation index group (≥14%) than in low proliferation index group (<14%)." (PMID 34679042, 2021). "The CD99 molecule has previously been linked to Rho GTPase activity, actin dynamics and growth factor signalling in breast cancer; EGFR stimulates RhoA and Rac1 activity and actin reorganization, and these pathways are antagonised by CD99-mediated signalling." (PMID 34374417, 2021). "Another recent study found that AKR1B10 can promote proliferation and migration/invasion of breast cancer cells via the ERK and FAK/Src/Rac1 signaling pathway." (PMID 34419144, 2021). "Next, we analyzed the expression pattern of RAC1 and BRD4 in different molecular subtypes of breast cancer." (PMID 34803511, 2021). "Taken together, these results suggest that combined inhibition of both RAC1 and BRD4 suppresses breast cancer cell growth and clonogenic potential." (PMID 34803511, 2021). "HACE1 controls cell migration in different cell types through degradation of active RAC1 at NADPH oxidase complexes, including in breast cancer cells, where HACE1 inhibits cell migration and invasion by targeting active RAC1." (PMID 33603169, 2021). "Earlier, we demonstrated that the RAC1 splice isoform, RAC1b, can protect cells from mesenchymal transition by TGFβ1 and an increase in TGFβ1 and RAC1-driven cell motility in both PDAC and breast cancer cells." (PMID 34771704, 2021). "Rencently, KRT19 was found to interact with β-catenin/RAC1 complex and regulated NUMB and Notch1 expression, leading to the enhancement of the cancer stem-like cell properties in breast cancer." (PMID 33442422, 2021). "In HER2‐positive breast cancers, one of the most aggressive subtypes of breast cancer, KCTD10 induces RhoB degradation and activation of Rac1, which promotes progression of tumors, and resistance to therapy." (PMID 34001146, 2021). "Moreover, it was found in another study that TQ could exert its own anti-proliferative effects on breast cancer cells via significant up-regulation of miR-32a by which expression of Rac1 was diminished in both in vitro (1 μg/mL) and in vivo (5 mg/kg of body weight) approaches." (PMID 34627167, 2021).
breast carcinoma (continued). "RAC1 analysis from breast cancer datasets GSE1379, GSE9195 and GSE9893 showed that high expression of RAC1 predicts poor survival of breast cancer patients." (PMID 34803511, 2021). "We also detected a correlation of RAC1 and BRD4 expressions with leukocyte infiltration and somatic copy number alteration (SCNA) in breast cancer samples." (PMID 34803511, 2021). "We observed higher expression levels of both RAC1 and BRD4 in different molecular subtypes of breast cancer in comparison to normal-like breast samples." (PMID 34803511, 2021). "We observed a reduction in RAC1 and BRD4 expressions in combination treated cells in comparison to control cell lines treated with DMSO in MCF-7, MDA-MB-231, SKBR3 and JIMT-1 breast cancer cells." (PMID 34803511, 2021). "Taken together, these results suggest that different molecular subtypes of breast cancer express high levels of RAC1 and BRD4 and amplification of both BRD4 and RAC1 signaling correlated with decreased survival of breast cancer patients." (PMID 34803511, 2021). "Prior studies have revealed the CCA-1.1 parent compound PGV-1 exerted an anti-migratory effect and lowered the MMP-9 and Rac-1 expressions in TNBC 4T1cells; this phenomenon was also presented in HER2+ breast cancer cells." (PMID 34181339, 2021). "In mammary cancer, KRT19 was reported to interact with β-catenin/RAC1 complex and then upregulate NUMB expression, thus suppressing Notch signaling." (PMID 33767587, 2021). "The depletion of estrogen receptor α (ERα) affects the biomechanical properties of Breast cancer (BC) cells, which is related to the decrease of cytoskeletal proteins (F-actin, FLNA, and α-tubulin) and cytoskeletal regulatory proteins (Rho, Rac1, and Cdc42)." (PMID 34079763, 2021). "Further investigation with the inhibitor showed that preventing Rac1 activation by ZINC69391 reduced EGF-induced actin reorganization and reduced cell migration as assayed by wound healing in MDA-MB-231 and F3II breast cancer cells." (PMID 32992837, 2020). "To translate this finding, we develop endosomal pH-responsive nanoparticles (NPs) which deliver Rac1-targeting siRNA together with cisplatin and effectively reverses NAC-chemoresistance in PDXs from NAC-resistant breast cancer patients." (PMID 32193458, 2020). "We experimentally validated the predicted miR-142-3p targets ROCK2, CFL2, RAC1, WASL, and ITGAV in St-T1b cells using qPCR, which is in accordance with our previous findings in breast cancer cells." (PMID 32824678, 2020). "In the Kaplan–Meier plotter bioinformatics analysis, higher expression of RAC1 and RRM2 were indicated to be an unfavorable prognostic factor for HER-2 positive breast cancer patients." (PMID 31895772, 2020). "In cultured breast cancer cells, Abi1 formed a complex with IRS53 to activate Rac1, which drives lamellipodial formation." (PMID 32728066, 2020). "RAC1 is upregulated in various cancers, such as LUAD, breast cancer, and kidney cancer, and the overexpression of RAC1 is frequently reported to be associated with worse prognosis." (PMID 33134373, 2020). "For instance, in the metastatic breast cancer cell line MDA-MB-231, CAV1-dependent activation of Rac-1 is observed in spreading assays." (PMID 32152405, 2020). "In breast cancer, a novel small molecule Rac1/Cdc42 dual inhibitor, MBQ-167, impaired STAT3 activation, resulting in decreased metastatic breast cancer cell migration." (PMID 32915198, 2020). "We also transfected breast cancer cells with specific siRNA for SOX2, NEDD9 or the Rac1 inactive mutant (T17 N) to investigate the role of SOX2, NEDD9 and Rac1 in the response to hypoxia." (PMID 31462898, 2019). "Collectively, these results show that Rac1 is required for SOX2- and NEDD9-mediated breast cancer cell migration under hypoxia." (PMID 31462898, 2019). "We found that specific genes such as CBL, RHOA, EP300, RAC1, CDK1, and CDH1 are involved in the migration and invasion of breast cancer." (PMID 30930932, 2019).
breast carcinoma (continued). "Overexpression and/or hyperactivation of RAC1’s immediate effector molecule, PAK, has been detected in several cancer types, including in breast cancer." (PMID 31027363, 2019). "Here, we propose a regulatory mechanism of breast cancer cell migration in that GAS7b interacts with CYFIP1 protein and prevents recruitment of Rac1-GTP to block actin polymerization, leading to the inhibition of motility of breast cancer cells." (PMID 29706651, 2018). "Overall, our results demonstrated that GAS7b suppressed breast cancer cells migration and invasion through inhibition of β1-integrin–FAK–Src signaling pathway, and the downstream Rac1 activity." (PMID 29706651, 2018). "We have previously reported that P-Rex1, which is highly expressed in luminal breast cancer cells, is the main Rac-GEF mediating Rac1 activation in response to ErbB receptor ligands." (PMID 29983884, 2018). "We have previously shown the effect of Rac1 inhibition by ZINC69391 and 1A-116 in breast cancer and glioma models, but Rac1 represents attractive innovative target for many other types of cancers." (PMID 29228706, 2017). "DOCK1 gene expression carries prognostic significance in breast cancer, ovarian cancer and glioblastoma multiforme through activation of c-JUN, STAT3, and Rac1." (PMID 29069784, 2017). "Depletion of Rac1b or Rac1 and Rac1b in MDA-MB-231 or MDA-MB-435s breast cancer cells by RNA interference enhanced or suppressed, respectively, TGF-β1-induced migration/invasion." (PMID 28726720, 2017). "In both breast and pancreatic cancer cells, RAC1 is a downstream effector of ERBB receptors and mediates migratory responses by ERBB1/EGF receptor (EGFR) ligands such as EGF or TGF-α and in breast cancer cells also by ERBB3 ligands such as heregulins." (PMID 28499439, 2017). "Immunohistochemical staining of RAC1 showed weak RAC1 expression in benign breast disease but high expression levels in DCIS, primary breast cancer, and lymph node metastases." (PMID 27902969, 2017). "Having demonstrated the mechanistic role of RAC1 activation in WP mediated ID-MA phenotypes in TNBC, we sought to define the relationship between RAC1 and outcome in ER-ve breast cancers." (PMID 27902969, 2017). "We confirmed that simvastatin caused the translocation of the small Rho GTPases RhoA, Cdc42, and Rac1/2/3 from cell membranes to the cytosol in U251 (glioblastoma), A549 (lung adenocarcinoma) and MDA-MB-231(breast cancer)." (PMID 28344327, 2017). "This study demonstrated for the first time that AKR1B10 promoted breast cancer metastasis through activation of the integrin α5 and δ-catenin mediated FAK/Src/Rac1 signaling pathway." (PMID 27248472, 2016). "Only recently was NC found to inhibit the phosphorylation of c-Src, FAK, MAPKs, and inhibit the activation of RhoA, Rac1, and AP-1 transcriptional activity induced by PDGF in breast cancer cells." (PMID 27821837, 2016). "This study also demonstrated that AKR1B10 promotes breast cancer metastasis through activation of the integrin α5 and δ-catenin mediated FAK/Src/Rac1 signaling cascade, in which the integrin α5 and δ-catenin function synergistically." (PMID 27248472, 2016). "Our results showing that SDF-1 activate Rac1 and induce MMP10 in breast cancer cells are in line with this finding." (PMID 27351228, 2016). "Activation of the small GTPases RAC1 and CDC42 mediating cell proliferation and migration has been demonstrated in many cancers, like breast cancer, prostate cancer, lung cancer, head and neck squamous cell carcinoma." (PMID 27120794, 2016). "As an activation of Src leads to an elevation of the complex consisting of p130Cas/Crk/Dock180 in breast cancer cells, ELMO1/Dock180 binding must be important for producing Src-dependent activation of Rac1." (PMID 26205662, 2015). "In Breast cancer cells MDA-MB-231, knockdown of RhoGDI2 results in Rac1 translocation from the cytosol to cellular membrane compartments, leading to constitutive Rac1 activation and cell growth inhibition." (PMID 25901126, 2015).